MACROD2 (mono-ADP ribosylhydrolase 2)
Description:
Removes ADP-ribose from aspartate and glutamate residues in proteins bearing a single ADP-ribose moiety. Inactive towards proteins bearing poly-ADP-ribose. Deacetylates O-acetyl-ADP ribose, a signaling molecule generated by the deacetylation of acetylated lysine residues in histones and other proteins.
Synonyms: C20orf133; dJ631M13.5; C2orf133
Tractability: Small molecule: a structure with a bound ligand is known. PROTAC: UniProt records ubiquitination sites on it; ubiquitination databases record sites on it; its protein half-life has been measured; a small molecule that binds it is known.
Target class: Enzyme; Hydrolase
Gene: Protein-coding gene on chromosome 20 (13,995,369 to 16,053,197, forward strand). Ensembl gene ENSG00000172264.
Subcellular location: Nucleus
Subcellular location (Human Protein Atlas): Nucleoli; Nucleoplasm
Gene Ontology:
Molecular function: ADP-ribosylglutamate hydrolase activity; deacetylase activity; hydrolase activity, acting on glycosyl bonds; O-acetyl-ADP-ribose deacetylase activity
Biological process: DNA damage response; peptidyl-glutamate ADP-deribosylation; protein de-ADP-ribosylation; purine nucleoside metabolic process; brain development
Cellular component: nucleolus; nucleoplasm; nucleus
Genetic constraint (gnomAD): Loss-of-function variants: 23 observed, 44.98 expected, observed/expected ratio (o/e) 0.51, 90% interval 0.37 to 0.72. The upper end of that interval is the gene's LOEUF score, 0.72, which puts it in group 2 of 6, group 1 being the genes least tolerant of losing a copy. Missense variants: 373 observed, 408.78 expected, observed/expected ratio (o/e) 0.91, 90% interval 0.84 to 0.99. Synonymous variants: 133 observed, 140.52 expected, observed/expected ratio (o/e) 0.95, 90% interval 0.82 to 1.09.
Homologues: Orthologues: macaque MACROD2 (97% identical), chimpanzee MACROD2 (93% identical), pig MACROD2 (83% identical), rabbit MACROD2 (83% identical), dog MACROD2 (82% identical), guinea pig MACROD2 (80% identical), mouse Macrod2 (75% identical), rat Macrod2 (75% identical), tropical clawed frog macrod2 (46% identical), zebrafish macrod2 (39% identical). Paralogues in human: MACROD1 (29% identical), GDAP2 (21% identical).
Diseases named in the same sentence as MACROD2 in open-access papers:
MACROD2 is named in the same sentence as 56 diseases in open-access papers, as found by Europe PMC text mining. Sharing a sentence is not in itself a finding about the gene and the disease. The quoted sentences say what the papers report.
autism (17 papers, 2012 to 2025). Persistent deficits in social interaction and communication and interaction as well as a markedly restricted repertoire of activity and interest as well as repetitive patterns of behavior. "Single nucleotide polymorphisms within MACROD2 have previously been associated with autism, although with rather weak evidence, and other brain-related traits such as intelligence and mathematical abilities." (PMID 31915053, 2020). "Single-nucleotide polymorphisms (SNPs) associated with autism are found in few candidate genes, among them the MacroD2 gene." (PMID 30991935, 2019). "In disease, MacroD2 shows association with neurological disorders, such as autism and kabuki syndrome (KS), as well as cancer." (PMID 30991935, 2019). "All CNVs intersecting genes were duplications, except for MACROD2, a gene previously linked to Autism." (PMID 23029476, 2012). "Indeed, studies consistently demonstrate associations between SNPs in the MACROD2 gene region and various diseases, including not only chronic diseases (cancer, hypertension, and obesity) but also neurological disorders (autism and Kabuki syndrome)." (PMID 35759225, 2022). "Indeed, several genome–wide association studies (GWAS) have reported links between MACROD2 and various neurological and psychiatric conditions such as autism, schizophrenia, ADHD as well as congenital heart defects (28% of which are linked to neurodegeneration)." (PMID 33578760, 2021). "CNVs involving the MACROD2 gene were detected in patients with attention deficit hyperactivity disorder, autism, and major depression with suicide attempts." (PMID 34659328, 2021). "We confirmed several loci responsible for Autism and Pervasive Developmental Disease including MACROD2, ITGB3, CADM2, and GRIK2." (PMID 25477900, 2014). "Many of these CNVs encompass genes included in the best‐known lists of candidate genes for autism, including CTNNA3 (OMIM #607667), MACROD2 (OMIM #611567), IMMP2L (OMIM #605977), PARK2 (OMIM #600116), LZTS2 (OMIM #610454), and LRP1 (OMIM #107770)." (PMID 37186221, 2023). "In the future, more in-depth cognitive and impulsivity testing, such as the radial arm maze, would provide further insight into the relevance of Macrod2 to ADHD, autism and schizophrenia to which the genomic locus has been linked." (PMID 33578760, 2021). "There were 3 VUS inherited from asymptomatic parents intersecting with genes within CNVs that have previously been implicated with disorders, such as CACNA2D1 with epilepsy and ID, and MACROD2 and LINGO2 with autism." (PMID 29441128, 2018). "The chr20 region (chr20p12.1) affects a relatively quiescent interval and a protein-coding gene expressed at low levels in iPSCs: MACROD2 (MACRO Domain Containing 2), a gene involved in autism and in tamoxifen resistance in breast cancer." (PMID 28410642, 2017).
Obesity (12 papers, 2018 to 2025). Accumulation of substantial excess body fat. "Meanwhile, human studies have shown that deletion of the MACROD2 gene exon was closely associated with obesity." (PMID 40665728, 2025). "Carriers of the minor allele of one mutation of MACROD2 reduced the risk of obesity and showed a trend toward a lower risk of BMI." (PMID 40244387, 2025). "Studies have shown that genetic variants in the MACROD2 gene were associated with hypertension in a Korean population, and the deletion of an exon in the MACROD2 gene was related to early onset of obesity." (PMID 37049393, 2023). "The MACROD2 gene has been associated with estrogen-independent growth and tamoxifen resistance in breast cancer patients, with obesity in the Korean population, and with autism spectrum disorder in the general population." (PMID 35102242, 2022). "Studies have demonstrated that the MACROD2 gene is associated with chronic diseases such as cancers, hypertension, and obesity." (PMID 35759225, 2022). "Altogether these data demonstrate that whole body deletion of MACROD2 gene is irrelevant for the insurgence and progression of obesity, and for its associated dysmetabolism." (PMID 30619475, 2018). "Non-coding and structural mutations/variations in MACROD2 have been associated to psychiatric disorders, to obesity, and to cancer." (PMID 30619475, 2018). "In addition, several genes were identified that are associated with obesity and play roles in lipid metabolism, including MACROD2, PHLPP2, CYP2E1, and STT3B." (PMID 40244387, 2025). "The MACROD2 gene has been reported to be associated with obesity in Koreans." (PMID 40244387, 2025). "Moreover, MACROD2 gene variants (rs6079275, rs6079272, and rs10470062) were associated with obesity in a Korean population." (PMID 37049393, 2023). "In an experimental study, they analyzed the epigenetic marks related to obesity and studied the blood methylation of the MACROD2 gene, which was positively associated with BMI levels, considering that the methylation of this gene may be involved in the development of obesity." (PMID 38140282, 2023). "Therefore MACROD2 could act as a transcriptional regulator of adipogenesis and obesity, in turn a major metabolic risk factor for developing cancer." (PMID 30619475, 2018). "For example, MACROD2, PHLPP2, CYP2E1, and STT3B are associated with obesity in the body, play a role in fat metabolism, and there is a close link between them and growth traits." (PMID 40244387, 2025). "Altogether, our data point against a sufficient role of MACROD2 deletion in aggravating high-fat induced obesity and DNA damage-associated lethality, in absence of other genetic drivers." (PMID 30619475, 2018). "Since silencing of MACROD2 significantly suppressed the expression of adipogenic genes in primary human pre-adipocytes, we hypothesized that MACROD2 could play a role in the development of obesity in vivo." (PMID 30619475, 2018). "Another gene, MACROD2, which is one of three mono ADP-ribosylases in humans, has been reported to act as a transcriptional regulator of adipogenesis and obesity in a Han population." (PMID 34572079, 2021). "Our study showed that Ruminococcus abundance was reduced in subjects with obesity, which might affect BMI through changes in DNAmet, specifically in a DMR located at the MACROD2 gene." (PMID 37049393, 2023). "High-fat diet administration induced obesity, and glucose/insulin intolerance in mice independent of MACROD2 gene deletion." (PMID 30619475, 2018). "In comparison with wild-type mice, no gross changes in HF diet-induced obesity are observed in MACROD2 KO mice." (PMID 30619475, 2018).
breast carcinoma (11 papers, 2013 to 2024). "MACROD2 copy number is increased in three different tamoxifen-resistant MCF7 breast cancer cell lines, prompting the authors to analyse MACROD2 expression in patient samples." (PMID 32151005, 2020). "In breast cancer, MACROD2 overexpression mediates estrogen-independent growth and tamoxifen resistance." (PMID 32257385, 2020). "The authors argue that, as a cancer specific fragile site, the MACROD2 gene can be lost, but this fragility also allows for amplification in the specific case of ER-positive breast cancers treated with tamoxifen to incur resistance." (PMID 32151005, 2020). "The authors observed amplification and overexpression of MACROD2 in tamoxifen-resistant breast cancer cell lines and in human breast cancer samples." (PMID 26426055, 2015). "This is particularly evident in breast cancer, where MACROD2 and FHIT are deleted in 28% and 15% of breast cancer cell lines, respectively, but either not at all (FHIT) or in only one out of 255 primary tumors (MACROD2)." (PMID 23805207, 2013). "MACROD2 is potentially relevant in ER-positive, tamoxifen resistant breast cancers where it may confer resistance to treatment." (PMID 32151005, 2020). "MACROD2 knockdown sensitizes tamoxifen resistant cells to tamoxifen treatment and reduces tumor formation of tamoxifen resistant cells in a xenograft model, suggesting that MACROD2 could become an important molecular target in the treatment of tamoxifen resistant breast cancer." (PMID 26426055, 2015). "Three of the regions were small, containing just one gene: chr17 - RAB11FIP4; chr20 - MACROD2, overexpression of this gene has been implicated in oestrogen-independent growth; and chrX - KLF8, oncogenic in ovarian but not breast cancer cell lines." (PMID 28095868, 2017). "Moreover, MACROD2 shows a significant effect in CRC and breast cancer." (PMID 39230704, 2024). "FHIT was co-deleted with MACROD2 in 75% of the cell lines with FHIT deletion, indicating that for certain breast cancer cell lines, replicative stress followed by DNA breakage and repair might occur during adaptation to cell culture and affect multiple common fragile site genes." (PMID 23805207, 2013).
colorectal cancer (8 papers, 2018 to 2023). A primary or metastatic malignant neoplasm that affects the colon or rectum. "Non-coding and structural variations in the MACROD2 gene have been associated with cancer predisposition, especially colorectal cancer, reported to alter DNA repair." (PMID 33810183, 2021). "Low expression of MACROD2 is associated with poor prognosis of colorectal cancer patients." (PMID 30619475, 2018). "The deletion of MACROD2 in colorectal cancer promotes chromosome instability and intestinal tumor growth." (PMID 32257385, 2020). "The removal of the autoinhibitory MAR moieties from PARP-1 by MacroD2 has been suggested to explain the accumulation of MARylated PARP-1 in the context of MacroD2 gene deletion in human colorectal cancer cells." (PMID 30862789, 2019). "In particular, the frequent deletions of mono-ADP-ribosylhydrolase 2 (MACROD2) locus in human colorectal cancer (CRC) alters DNA repair and the sensitivity to DNA damage and results in chromosomal instability." (PMID 31921812, 2019).
Hypertension (7 papers, 2019 to 2024). The presence of chronic increased pressure in the systemic arterial system. "In a study of 1,100 Han Chinese individuals from 398 families in the Stanford Asian Pacific Program for Hypertension and Insulin Resistance study, genetic loci within the MACROD2 gene were associated with vascular adhesion protein-1 levels (VAP-1) in females." (PMID 32894123, 2020). "Additionally, the genotype distributions of the MACROD2 rs616996211 and rs6034240 polymorphisms were found to have a significant association with hypertension in the Korean population." (PMID 39202079, 2024). "FLRT3 locates on chromosome 20 and is transcribed from the negative -strand in a region overlapping with MACROD2, a gene which polymorphism has been associated with the risk of coronary artery disease and hypertension." (PMID 30930791, 2019).
autism spectrum disorder (6 papers, 2012 to 2024). A spectrum of developmental disorders that includes autism, and Asperger syndrome. "The MACROD2, which was the neurodevelopmental-related gene, was reported as the risk loci of autism spectrum disorder, while the autism spectrum disorder had overlapping mechanisms of pathogenesis with AD." (PMID 36553611, 2022). "Therefore, we suggested that the MACROD2 was associated with AD by affecting the autism spectrum disorder." (PMID 36553611, 2022). "As, so far, only be detected in the brain, the MACROD2 has been reported to correlated with autism-spectrum disorders, which is supported by behavioral phenotypes observed in MACROD2 gene knockout mice model." (PMID 38734665, 2024). "Our most significant gene, MACROD2, which we also replicated in a new cohort, was recently discovered in the context of autism spectrum disorder (ASD), as the gene containing the top SNP (p < 5 × 10−8) in a GWAS of 1,558 families of whom some members had been diagnosed with ASD." (PMID 22888310, 2012).
schizophrenia (4 papers, 2012 to 2021). A major psychotic disorder characterized by abnormalities in the perception or expression of reality. "MACROD2 has also been associated with schizophrenia, as the gene corresponding to a rare, copy number variant in a linkage analysis." (PMID 22888310, 2012). "In addition to novel GWS loci, we have identified a significant genetic correlation with schizophrenia and association of ASD with several neurodevelopmental-related genes such as EXT1, ASTN2, MACROD2, and HDAC4." (PMID 28540026, 2017).
colon cancer (3 papers, 2013 to 2018). "The current study showed that low MACROD2 protein expression was associated with poor DFS in stage III MSS colon cancer patients who received 5-FU-based adjuvant chemotherapy." (PMID 30034629, 2018). "In conclusion, loss of nuclear MACROD2 protein expression predicts poor response to adjuvant 5-FU-based chemotherapy in MSS stage III colon cancers." (PMID 30034629, 2018). "Stratification by MSI status showed that in microsatellite stable (MSS) stage III colon cancers (n=109) low expression of MACROD2 was associated with poor DFS (p=0.02; HR=2.0, 95% CI 1.1-3.7)." (PMID 30034629, 2018). "We examined the effects of A2BP1 and MACROD2 deletions on underlying gene expression in colon cancers and normal colon tissues." (PMID 23805207, 2013). "MACROD2-low colon cancers were associated with higher N-stage (p=0.03)." (PMID 30034629, 2018). "Loss of nuclear MACROD2 protein expression in epithelial neoplastic cells of stage III microsatellite stable (MSS) colon cancers was associated with poor DFS within the subgroup of 59 patients who received 5-fluorouracil (5-FU)-based adjuvant chemotherapy (p=0.005; HR=3.8, 95% CI 1.4-10.0)." (PMID 30034629, 2018). "However, loss of MACROD2 protein expression was strongly associated with poor DFS in MSS stage III colon cancer patients that did receive 5-FU-based adjuvant chemotherapy (p=0.005; HR=3.8, 95% CI 1.4-10.0)." (PMID 30034629, 2018). "Further studies are warranted to validate this potential biomarker to stratify colon cancer patients for response to 5-FU-based chemotherapy in the clinic and to dissect the putative essential function of MACROD2 with respect to therapy resistance." (PMID 30034629, 2018). "The limited numbers of MSI stage II (n=33) and stage III (n=23) samples did not allow for meaningful comparison of DFS in MACROD2-low versus MACROD2-high MSI colon cancers." (PMID 30034629, 2018). "Tissue microarrays (TMA) containing formalin-fixed paraffin-embedded tissue cores from 386 clinically well-annotated primary stage II and III colon cancers were stained by immunohistochemistry and evaluated for MACROD2 protein expression." (PMID 30034629, 2018). "In this study, we aimed to investigate the association of MACROD2 protein expression with clinical outcome in stage II and stage III colon cancer." (PMID 30034629, 2018). "The observation that MACROD2 expression was predictive in colon cancers treated for 5-FU-based adjuvant therapy may suggest that the underlying biological mechanism is involvement of MACROD2 in DNA damage response, which is one of the known functions of MACROD2." (PMID 30034629, 2018). "Although this study comprised a large retrospective cohort of 343 stage II and stage III colon cancer patients with well-documented clinical information, the sample size was insufficient to extensively test interactions of MACROD2 expression with other clinicopathological parameters." (PMID 30034629, 2018). "However, since MACROD2-low expression was associated with poor DFS in the subgroup of stage III colon cancer patients who received 5-FU-based adjuvant chemotherapy, two separate models were built for stage II and stage III colon cancers." (PMID 30034629, 2018). "In both studies MACROD2 is the gene that is most frequently affected by chromosomal breaks, i.e. in 35% of stage II and III colon cancer samples in the present dataset and in 41% of advanced CRCs." (PMID 27729614, 2016). "Prognostic value of MACROD2 protein expression was examined by evaluation of immunohistochemical staining on TMAs that contained tissue biopsies from 226 stage II and 160 stage III colon cancers." (PMID 30034629, 2018). "While MACROD2 expression was not retained by the model in stage II colon cancers, MACROD2 expression was retained in the multivariate model for stage III colon cancers in addition to ‘tumor location’, ‘T-stage’, ‘angioinvasion’ and ‘perforation’." (PMID 30034629, 2018).
colon cancer (continued). "Besides MACROD2, 23 recurrent breakpoint genes (FDR < 0.1) were detected at a relatively high prevalence, affecting more than 10% of colon cancer samples." (PMID 27729614, 2016). "The fact that MACROD2 was readily detected as a common fragile site gene in colon cancer cells but not in lymphocytes is consistent with prior evidence that different cell types show different profiles of common fragile sites." (PMID 23805207, 2013). "This establishes that MACROD2, which was not previously shown to be a common fragile site gene in lymphocytes, is indeed a common fragile site gene when assayed in a colon cancer cell line." (PMID 23805207, 2013). "Interestingly, we found that colon tumors were by far the most frequently affected by focal deletions in CFS-like genes, with deletion frequencies as high as 21% for A2BP1, 17% for MACROD2, 9% for FHIT and 9% for PARK2." (PMID 23805207, 2013).